CD82 (CD82 molecule)
Diseases named in the same sentence as CD82 in open-access papers (continued):
Sharing a sentence is not in itself a finding about the gene and the disease.
cancer (continued). "Together, our data suggest that the ectopic expression of CD82 significantly reduces the levels of sLex/a, which in turn reduces the adhesion of cancer cells to blood vessels." (PMID 25923697, 2015). "The majority of evidence indicates that KAI1/CD82 expression is downregulated or abolished in a variety of malignant tumors." (PMID 26408312, 2015). "In this study, we focused on the effects of the metastasis suppressor CD82/KAI1 on heterocellular adhesion of cancer cells to the endothelium of blood vessels in order to further elucidate the function of tetraspanins." (PMID 25923697, 2015). "Although the KAI1/CD82 gene has been reported to be involved in numerous other cancer types, its involvement in NPC is largely unclear." (PMID 25789023, 2015). "In our in vivo metastasis assay, CD82 showed a strong inhibitory effect on the size and number of lung metastasis foci following the direct injection of cancer cells into the mouse tail vein." (PMID 25923697, 2015). "We have recently elucidated a novel function for CD82 in E-cadherin-mediated homocellular adhesion; due to this function, it can inhibit cancer cell dissociation from the primary cancer nest and limit metastasis." (PMID 25923697, 2015). "Several strategies have been employed to re-express KAI1/CD82 in cancer cells via targeting its transcription." (PMID 26431493, 2015). "In malignant solid tumours, the expression of CD82/KAI1 strongly correlates with a better prognosis for cancer patients, whereas its down-regulation is commonly found in clinically advanced cancers." (PMID 25923697, 2015). "The over-expression of CD82 in cancer cells led to the inhibition of experimentally induced lung metastases in mice and significantly inhibited the adhesion of these cells to human umbilical vein epithelial cells (HUVECs) in vitro." (PMID 25923697, 2015). "The KAI1 gene, also known as CD82, is a membrane of the tetraspanin superfamily and is regarded as a metastasis-suppressor gene in several types of cancers." (PMID 23762858, 2013). "The role played by CD82 in cancer progression was discovered during a genetic screen to identify metastasis-suppressor genes." (PMID 23076981, 2012). "This is a novel function of CD82 in E-cadherin-mediated homocellular adhesion and one of the most important functions of CD82 in inhibiting cancer metastasis." (PMID 23076981, 2012). "To date, the inhibitory role of CD82 in cancer progression has been well established and related molecular mechanisms have been intensively studied." (PMID 22679510, 2012). "In conlusion, CD82 suppresses cancer metastasis through the canonical Wnt pathway via multifunctional ways." (PMID 23076981, 2012). "The role of CD82 in inhibiting cancer progression was discovered during a genetic screen to identify metastasis suppressor genes." (PMID 22679510, 2012). "β-catenin serves as a co-repressor of expression of prostate cancer metastasis repressor gene KAI1 (CD82)." (PMID 22511927, 2012). "Overall, accumulating evidence of the anti-metastatic effect of CD82 suggests CD82 as a novel therapeutic target for anti-metastasis cancer therapy." (PMID 23076981, 2012). "Our previous studies indicate that CD82 negatively controls cancer cell migration and proteinase secretion by regulating cell signalling events, particularly those mediated by receptor tyrosine kinase (RTK) and phosphoinositide 3-kinase (PI3K)." (PMID 23076981, 2012). "By employing RT-PCR and immunohistochemistry, we studied the expression of CD9, CD63 and CD82 in 49 paired tissue specimens of normal gastric mucosa and carcinoma." (PMID 21521534, 2011). "Previously, we showed that reductions of MRP-1/CD9 and KAI1/CD82 were predictive factors for a poor prognosis in patients with various kinds of cancers." (PMID 12838318, 2003).
cancer (continued). "Although the mechanisms of action of the transmembrane superfamilies, motility-related protein-1 (MRP-1/CD9) and KAI1/CD82, are not well known, they are reported to suppress the metastasis of several kinds of cancers." (PMID 10098753, 1999). "A total of 16% of studies showed that CD82 expression varied during cancer progression." (PMID 38473906, 2024). "To further confirm our results that the effects of p65KD on the expression of the epithelial cell phenotype were mediated through CD82, we knocked-down the expression of CD82 in RelA/p65KD A549 cancer cells using the control retroviral vector pSIREN-ZsGreen or pSIREN-ZsGreen-shCD82." (PMID 34503110, 2021). "Co-culture of HCC cells and vein endothelial cells suggests that CD82 may mediate the communication between cancer cells and endothelial cells." (PMID 34540692, 2021). "CD82 inhibits cancer cells dissemination from primary tumors by promoting cell-cell adhesion." (PMID 32483464, 2020). "Similarly, CD82 expression was frequently downregulated or lost in poorly differentiated cancers or at the advanced stage of cancers." (PMID 32091301, 2020). "The mechanisms that lead to CD82 downregulation in cancer still remain poorly characterized." (PMID 32483464, 2020). "Cancer-associated exosomes opt to transport specific transmembrane proteins, including integrins and tetraspanins such as CD9, CD63, CD81, and CD82 that are specifically recognized by target cells, which can explain the high rate of exosomal uptake by cancer-adjacent stromal cells." (PMID 32121073, 2020). "CD82 is a highly glycosylated protein, however, it is still unknown whether and how this post-translational modification affects CD82 function and cancer metastasis." (PMID 32483464, 2020). "Here, we showed upregulation of GALNT14 in CD82 restored metastatic prostate cells and it is uncertain whether adding CD82 caused methylation that increased GALNT14 expression in those cells, as seen in many cancers or is due to some other mechanism." (PMID 33298014, 2020). "Moreover, these drugs either diminish or induce expression of CAM, like EpCAM or CD82, which were altered through cancer initiation, progression and metastasis." (PMID 30289336, 2019). "CD82 expression in serum exosomes is also positively correlated with cancer clinical stage." (PMID 31355262, 2019). "CD82, or KAI1, expression is decreased or abolished in various malignant tumors." (PMID 31483122, 2019). "Importantly, we show that in all these cancer cells liprin-α1 knockdown leads to the upregulation of transmembrane protein CD82, which is a suppressor of metastasis in several solid tumors." (PMID 30005669, 2018). "Thus, we believe that TIMP-1 plays a role in the suppression of cancer cell migration by interacting with CD82." (PMID 28030805, 2017). "CD82 was mainly expressed in the cytomembrane of cancer cells." (PMID 28881668, 2017). "CD82 is also known to suppress metastasis during cancer progression." (PMID 26132195, 2015). "Thus, our results strongly suggest an inhibitory role for CD82 in the adhesion of cancer cells to vascular endothelial cells." (PMID 25923697, 2015). "CD82 regulates cell aggregation, cell motility, cancer metastasis, and apoptosis." (PMID 25923697, 2015). "KAI1/CD82 acts as metastasis suppressor in many malignant tumors." (PMID 26431493, 2015). "Moreover, miR-203 also regulated cell migration, a critical component of metastatic progression, in cancer cells through CD82." (PMID 26132195, 2015). "Similarly, down-regulation of the metastasis suppressor CD82 is correlated with cancer progression and poor survival in patients." (PMID 19671175, 2009). "Although the precise biological functions of these proteins remain unknown, the downregulation of KAI1/CD82 and MRP-1/CD9 genes during the progression of human cancer is highly associated with a poor prognosis." (PMID 12838318, 2003).
cancer (continued). "This is interesting as a β-catenin/Reptin complex was found to represses CD82 transcription and also NF-κB activation, suggesting the existence of a feed-forward mechanism whereby an increase in β-catenin inhibits CD82 expression to enhance Wnt signalling and cancer metastasis." (PMID 34503110, 2021). "In summary, KAI1/CD82 may be considered a significant prognostic marker in predicting metastatic manifestation and may be a promising and effective candidate for treatment for certain cancers." (PMID 34306081, 2021). "However, the exact mechanism by which CD82 prevents cancer metastasis is unclear." (PMID 33298014, 2020). "Thus, CD82 is found downregulated in many metastatic human cancers." (PMID 33298014, 2020). "CD82 has been reported to be significantly overexpressed in BPH associated with cancer when compared to BPH not linked to cancer and thus CD82 overexpression may restrict PCa development while its loss may predispose the patient to more aggressive disease." (PMID 29674723, 2018). "CD82, a member of the tetraspanin protein family, has previously been shown to interfere with cancer proliferation, invasion and migration, and it has been supported by an inverse correlation between its expression levels and the metastases of a variety of human cancers." (PMID 28881668, 2017). "Although the precise mechanisms for regulation of CD82 remain unclear, down-regulation rather than mutation is the most common mechanism in the progression of many cancers." (PMID 21521534, 2011). "We confirmed an increase in cytotoxicity against target cancer cells when CD81 and CD82 were overexpressed in the T cells." (PMID 38515751, 2024). "To explore the impact of T-cell activation and cytokine expression on cancer cell cytolysis, particularly that influenced by CD81 and CD82, as observed in our preceding results, we embarked on a series of investigations." (PMID 38515751, 2024). "The following TSPANs have been involved in enhancing cancer therapy resistance: CD9, CD81, TSPAN1, TSPAN3, TSPAN31, CD82 and CD63." (PMID 36941633, 2023). "TSPAN1, TSPAN3, TSPAN12, TSPAN31, CD82 and CD63 have also been reported to reduce chemosensitivity of cancer cells." (PMID 36941633, 2023). "We also observed re-expression of CCND2, CD82 and IGF1R in three out of four models, which was already described after azacytidine treatment in several cancers." (PMID 36765607, 2023). "With the epigenetic inactivation of KAI1/CD82 in at least ten additional solid human cancers, this implies a very good chance to broaden the spectrum of human cancers affected by our compounds." (PMID 37990044, 2023). "Based on the available evidence, CD81 and CD82, and TSPAN6 can serve as cancer suppressors, while CD151, TSPAN1, and TSPAN8 act as cancer promoters in the diagnosis and prognosis of HCC patients." (PMID 34540692, 2021). "For the development of exosome-based early diagnosis and analysis of cancers, tetraspanins (such as CD9, CD63, CD81, and CD82) are typically utilized as the capturing molecules for the detection of cancer-associated exosomes." (PMID 33803846, 2021). "CD82, also known as KAI1, is a member of the tetraspanin superfamily and has been identified as a potent inhibitor of cancer metastasis." (PMID 32483464, 2020). "Among the human tetraspanins, Tspan8 and 12, CD9, CD37, CD63, CD81, CD82, and CD151 play a role in cancer progression." (PMID 29946318, 2018). "Our findings shed light on a new ligand–microdomain transmembrane signal transduction platform on cell surface, and highlight dynamic cross-talk between extracellular fluid and cancer cells mediated by TIMP-1 and CD82." (PMID 28030805, 2017). "CD82 directly binds to TIMP-1 N-terminal region through its large extracellular loop and co-localizes with TIMP-1 in both cancer cell lines and clinical samples." (PMID 28030805, 2017).
cancer (continued). "Their co-localization was significantly enhanced both on surface of and inside the carcinoma cells, although both normal breast epithelial cells and DCIS demonstrated co-localization of TIMP-1 and CD82." (PMID 28030805, 2017). "Some tetraspanins such as CD82, and often also CD9, are downregulated in advanced stages of cancer; their absence is a sign of poor prognosis in patients with several types of cancer." (PMID 27243007, 2016). "Another receptor tyrosine kinase that is suppressed by KAI1/CD82 is c-Met (also known as the hepatocyte growth factor receptor; HGFR), which is involved in oncogenic signaling in cancer cells." (PMID 26431493, 2015). "We concluded that CD82 decreases sLea/x expression via the down-regulation of ST3GAL4 expression and thereby reduces the adhesion of cancer cells to blood vessels, which results in inhibition of metastasis." (PMID 25923697, 2015). "Presently, CD133 is one of the hottest markers to characterize cancer stem cells and KAI1/CD82 is reported as an important marker for the metastasis and prognosis of many cancers." (PMID 24758564, 2014). "In all, 63 carcinomas (43.2%) were evaluated as KAI1/CD82-positive and 83 carcinomas (56.8%) as KAI1/CD82-negative expression." (PMID 12838318, 2003). "Furthermore, it has been observed that both CD81 and CD82 influence cytokine production in CD4 cells and affect cytotoxicity against cancer cells in CD8 cells." (PMID 38515751, 2024). "The three PIMs with CD82 were upregulated specifically in Th17 cells when compared with naive, T follicular helper (Tfh), Treg, and exhausted cytotoxic T cells within the CD4+ fraction of patients with cancer." (PMID 38039135, 2023). "Thus far, DNA hypermethylation in cancer cells has been documented for at least 6 members of the tetraspanin family, including CD9, CD81, CD82, CD151, TSPAN1, TSPAN3, and Uroplakin." (PMID 33919420, 2021). "The importance of CD82/KAI1 in malignant cancer progression has been supported by an inverse correlation between its expression levels and the metastases of a variety of human cancers." (PMID 27926483, 2017). "Despite wide investigations, many aspects of how CD82/KAI1 specifically suppresses cancer metastasis are not yet fully determined." (PMID 27926483, 2017). "CD82/KAI1, a member of the tetraspanin superfamily, was first identified as a T-cell accessory molecule and subsequently identified in a genetic screen for cancer metastasis suppressor genes." (PMID 25923697, 2015). "Therefore, we conclude that CD82 down-regulates ST3GAL4 and regulates sialyl Lewis antigen-mediated cancer cell adhesion to blood vessels and, thereby, the inhibition of cancer cell metastasis." (PMID 25923697, 2015). "Also, there was a significantly increasing trend in the mean OS survival time and DFS time between the carcinomas with the expression of KAI1/CD82 and those without (P < 0.001, P < 0.001)." (PMID 24758564, 2014). "Furthermore, 17 carcinoma tissues (34.7%) were evaluated as CD82 positive and 32 carcinomas (34.7%) as CD82 negative." (PMID 21521534, 2011). "The expression of both MRP-1/CD9 and KAI1/CD82 were positive on the cell membranes of normal oesophageal epithelial cells, but reduced or negative in the cancer cells." (PMID 10098753, 1999).
infection (10 papers, 2013 to 2025). The state of being infected such as from the introduction of a foreign agent such as serum, vaccine, antigenic substance or organism. "Again, there was little difference in susceptibility to infection between the cell lines, with CD82 null cells if anything showing reduced infection." (PMID 32253503, 2020). "CD82 knockout macrophages lead to larger lesions upon L. mexicana infection, demonstrating the role of this tetraspanin in infection control." (PMID 36982564, 2023). "CD82 is a cell surface tetraspannin, expressed on a variety of leukocyte cells including T cells, is downregulated in infection and correlates with increased leukocyte motility." (PMID 32318053, 2020). "We found a strong interaction between RUNX1 and CD82 promoter regions in BMDMs after MTB Rv infection." (PMID 29760437, 2018). "RNA-seq and quantitative real-time PCR analyses showed that CD82/KAI1 were the most significantly upregulated genes expressed in MTB Rv versus MTB Ra infection." (PMID 29760437, 2018). "CD82 expression was markedly increased by the dose-dependent inhibition of DNA methylation following infection with MTB, which was confirmed by western blotting." (PMID 29760437, 2018). "Interestingly, the CD82 null macrophages were significantly more prone to forming MNGC on infection with both strains of B. thailandensis." (PMID 32253503, 2020). "Interestingly, the initial investigations showed that macrophages from CD82 null mice were also more prone to forming MNGC on infection with B. thailandensis." (PMID 32253503, 2020). "In this study, CD82 interacted with a number of host cell proteins, including enzymes, and a broad spectrum of structural and functional subcellular organellar proteins, revealing a new facet of the role of CD82 in the regulation of innate host infection and immune responses." (PMID 29760437, 2018). "Compelling evidence indicates that the large extracellular loop (LEL) of mast cell-expressed TET proteins [Cluster of differentiation (CDs), such as CD9, CD63, CD81, CD82, CD151] plays a key role in the route of pathogens infection." (PMID 35310653, 2022). "Here, we suggested a novel role for CD82 in regulating inflammatory signaling and the intracellular survival of MTB during infection in murine and in human TB lesions." (PMID 29760437, 2018). "Our results partly correlate with those of a previous study showing that RUNX1 binds to CD82 in macrophages and suppresses MTB-induced infection and inflammation." (PMID 29760437, 2018). "After infection with a high intravenous dose of MTB Rv, CD82−/− mice showed an increased survival rate (median survival, 90 days) compared with CD82+/+ mice (median survival, 70 days)." (PMID 29760437, 2018). "In the MTB-containing phagosome fraction, CD82 interacted strongly, although transiently (3–6 h), with endogenous Rab5 and Rab22, but not with Rab7 after infection with MTB Rv, and vice versa (data not shown)." (PMID 29760437, 2018). "Notably, the tetraspanin with the highest significant differences in expression was also CD82, since no expression in B cells was detected in the patients with infections." (PMID 36982564, 2023). "Many genes associated with the cell death such as tumour necrosis factor receptor (Tnfrsf1a), inhibitor of kappaB kinase (Ikbkg), kinases (Cd82 and Cdk2), and apoptosis regulator (Bcl2l1 and Birc2) were only up-regulated in WT infection and showed no expression in BM16 infection." (PMID 27634329, 2016). "Interestingly, the same percentage of CD82-positive virus-containing vesicles was observed in the three DC subsets, suggesting that HTLV-1 might be stored in similar compartments despite a different infection outcome." (PMID 28426803, 2017).
digestive tumor (1 paper, 2024). "Generally, the expression of Tspan7, CD82, Tspan9, and CD63 are downregulated suppress the migration and invasion of digestive system tumor cells." (PMID 38389703, 2024). "Several studies have demonstrated that CD82 inhibits EMT and metastasis of digestive tumor cells through binding to extracellular matrix (ECM)-related molecules such as integrin and metalloprotease, and subsequently regulating their downstream signal transductions." (PMID 38389703, 2024).
infectious disease (1 paper, 2018). A disorder directly resulting from the presence and activity of a microbial, viral, or parasitic agent in humans. "Further study is required to examine the diverse array of functions of CD82 and RUNX1, the complexity of the regulation of CD82–RUNX1–Rab5/22, and the prospects for targeting CD82 as a therapeutic approach for the treatment of various infectious diseases." (PMID 29760437, 2018).
retinal disorder (1 paper, 2022). Any disease or disorder of the retina. "Taken together, this finding suggested that rhCD82 suppressed TGF-β1-induced EMT of RPE by blocking of Smad-dependent pathway, which is caused by rhCD82 interaction with TGFRs and integrins, suggesting new insight into CD82 as a potential therapeutic strategy in fibrotic retinal disorders." (PMID 36386228, 2022).